UBC (ubiquitin C)
Diseases named in the same sentence as UBC in open-access papers (continued):
Sharing a sentence is not in itself a finding about the gene and the disease.
cancer (continued). "Interestingly, the UBC gene dominates all of the targeted genes associated with early- and late-stage NSCLC, so its role in the cancer pathway warrants further investigation." (PMID 26817825, 2016). "Overall, it appears that UBC, by controlling protein degradation through UPS, plays a significant role in cancer initiation and evolution." (PMID 38891892, 2024). "For example, cancer cell lines with low UBB expression show elevated UBC levels, and inhibiting UBC induces UBB expression." (PMID 37350942, 2023). "Consistent with other cancer types, there was abundance of stress tolerance with expression of HBB and ubiquitin C (UBC)." (PMID 32655131, 2020). "The role of MAPK15 and UBC in tumorigenesis has been reported in many previously discussed scientific works, while SMIM28 is a less studied gene with an unclear role in cancer." (PMID 33245713, 2020). "Despite their recognized role in cell survival and proliferation, little is known about the molecular mechanisms regulating UBC and UBB gene expression in cancer cells." (PMID 32751694, 2020). "The cross-tissue analysis of 12 cancer types revealed that the most stably expressed genes were: PUM1 (SExp = 70), IPO8 (SExp = 61), UBC (SExp = 60), ACTB (SExp = 55), and RPN1 (SExp = 54)." (PMID 30881377, 2019). "The central location of UBC in the network of interactions between the hub genes suggests that alterations in ubiquitination may mediate many of the cellular effects of smoking, in line with the evidence described in the preceding paragraph in relation to cancer and cardiovascular diseases." (PMID 26837704, 2016). "To generate stable fluorescent sensors that can identify carcinoma cells with EMT or MET properties, we used the lentiviral expression vector FUGW, which expresses eGFP from the constitutively active ubiquitin C (UbC) promoter." (PMID 27317311, 2016). "In contrast, for the three reference genes (B2M, TBP and UBC), neither or only one of the two guide RNAs (gRNAs) targeting each gene showed increased repression fold changes in cancer." (PMID 39478119, 2024). "Several genes (B2M, EIF2B1, ELF1 and PSMC4; type 1 EC, and YWAZ, UBC, and PGK1; type 2 EC) were not identified in the combinations of five best genes for the two cancer sub-types (this study) suggesting that the transcriptome of these two EC sub-types may in fact be very different." (PMID 32439920, 2020). "Interestingly, the expression levels of both NF-κB and UBC were not significantly altered in KIRC, instead they highly interconnect with other genes in the network structure, suggesting their important regulatory roles in the cancer." (PMID 25559354, 2014). "Interestingly, we observed that GAPDH, GUSB, IPO8, RPL13, RPL32, and UBC genes, as well as RPLP0 + TBP, RPL13 + RPL32, RPL13 + RPLP0, and ACTB + TBP RG pairs, were the only assays whose expression did not depend (P > 0.05) on cancer progression." (PMID 25225161, 2014).
infection (10 papers, 2008 to 2024). The state of being infected such as from the introduction of a foreign agent such as serum, vaccine, antigenic substance or organism. "For PMMoV infection, RefFinder identified the top four stable reference genes as RdR6, UBC, Tspan, and ACT while the least stable were AGO2, PGK, and L23, none of which were suitable as a reference gene." (PMID 36840204, 2023). "Fischer 344 rats expressing human APP driven by the ubiquitin-C promoter were generated via lentiviral vector infection of Fischer 344 zygotes." (PMID 18302776, 2008). "Expression of these constructs tagged with Tdtomato (FUtdTW) were driven by the Ubiquitin C (UbC) promotor, in the primary culture of mNPCs in vitro by lentivirus (FUtdTW) infection in 48-h culture and pulse-labelled with EdU for 3 h before harvesting the cells." (PMID 39137170, 2024). "Finally, there is one gene UBC with an overtaking threshold basal level, indicating that this might have been resulting in DNA methylation via infection progression." (PMID 30769958, 2019). "For example, while Lip, eIF4A, EF1α, and L23 appeared to be most suitable as reference genes for infection by TMV, those most suitable for PMMoV (another tobamovirus) were RdR6, UBC, Tspan, and ACT." (PMID 36840204, 2023). "Therefore, for the rose, we propose the use of PP2A, UBC (and GAPDH) for the expression analysis of different tissues and SAND, UBC (and TIP) for the analysis of stress treatments such as wounding, heat stress and infection by pathogens." (PMID 22123042, 2011).
cardiovascular disease (3 papers, 2011 to 2016). "An examination of the literature and annotated disease databases indicates that TRAF2, SHKBP1 and UBC have not been widely investigated in the context of cardiovascular disease, and that no quantitative links have been made to clinical response after MI." (PMID 21756327, 2011).
neurodegenerative disease (3 papers, 2015 to 2025). A disorder of the central nervous system characterized by gradual and progressive loss of neural tissue and neurologic function. "UBC, RPL4, and HSPA1A were identified as common hub genes, indicating their central role in the intersected network of dysregulated astrocytic genes across multiple neurodegenerative diseases." (PMID 40244314, 2025).
psychiatric disorder (2 papers, 2013 to 2014). A disorder characterized by behavioral and/or psychological abnormalities, often accompanied by physical symptoms. "The core interactor, UBC (Ubiquitin C), is a protein with large number of natural binding partners (n = 8750) thus interaction is unlikely to be specific for psychiatric disorders." (PMID 25414627, 2014).
genetic disease (1 paper, 2017). "In conclusion, we propose here a methodology that may be used for some other genetic disease with great variability and identify new candidate modifier genes in CF, related to lung, pancreas and liver, such as Ubiquitin C." (PMID 28339466, 2017).
metabolic disease (1 paper, 2014). A congenital disorder (due to inherited enzyme abnormality) or acquired (due to failure of a metabolically important organ) disorder resulting from an abnormal metabolic process. "Amongst the significant networks that we identified, NF-κB and UBC are examples of central nodes for molecular transport, hereditary disorder, metabolic disease network and network of renal or urological disease." (PMID 25559354, 2014).
neurological disease (1 paper, 2012). "The last pathway is involved in neurological disease, developmental and hereditary disorders with central proteins being UBC, p38 MAPK and Akt, which are involved in various pathological conditions." (PMID 22876852, 2012).
urological disease (1 paper, 2014). "UBC (ubiquitin C), a gene associated with protein degradation, DNA repair and cell cycle regulation, is located at the centre of the renal and urological disease network, and interconnects many other genes in the network as a hub protein." (PMID 25559354, 2014).
UBC also shares sentences with these, for which no sentence is quoted: depression (2 papers); glioblastoma (2); lung adenocarcinoma (2); multiple myeloma (2); adenocarcinoma (1); allergic rhinitis (1); Ataxia (1); autism (1); bacterial infection (1); bipolar disorder (1); carcinosarcoma (1); cervical cancer (1); chronic pancreatitis (1); colon adenocarcinoma (1); colorectal (1); eczema (1); epilepsy (1); fungal keratitis (1); Glucose intolerance (1); gynecological tumor (1); Heat Stroke (1); Hepatic steatosis (1); Hypercholesterolemia (1); Intellectual disability (1); Krabbe disease (1); liver failure (1); medulloblastoma (1); megalencephalic leukoencephalopathy (1); mesothelioma (1); muscle atrophy (1).
A further 9 diseases each share a sentence with UBC in 1 paper.